TNF (tumor necrosis factor)
Diseases named in the same sentence as TNF in open-access papers (continued):
Sharing a sentence is not in itself a finding about the gene and the disease.
colitis (continued). "Treatment with rSj-Cys significantly reduced TNBS-induced experimental colitis in mice through upregulation of Treg cells and related cytokines IL-10 and TGF-β, and downregulation of pro-inflammatory cytokines TNF-α and IL-6 in the colon tissues of mice." (PMID 32423469, 2020). "Although TNF-α and IFN-γ are known to enhance the immunosuppressive properties of ASCs12, the therapeutic efficacy of EVs produced from ASCs pretreated with TNF-α and IFN-γ in colitis is unclear." (PMID 32034203, 2020). "This suppression of TNF-α levels agrees with a previous study during, in which the effect of IMD on a DSS-induced mouse model of colitis was investigated." (PMID 31731774, 2019). "Oral administration of AL-1 significantly attenuates the production of IL-1β, IL-6, TNF-α, PGE2, and IFN-γ in the sera of colitis mice." (PMID 31687082, 2019). "Consistent with increased access of these pro‐inflammatory factors, serum levels of IL‐1β, TNF‐α and IL‐6 were elevated in DSS‐treated mice, which were drastically reduced in mice colitis model following CHC treatment." (PMID 31418947, 2019). "The levels of TNFα, IL-1β, and IL-6 in colon tissues of WT mice remained high at d 6 post DSS challenge, correlated with severe tissue damage and worse colitis outcome as observed above." (PMID 31555304, 2019). "When colitis was concomitantly induced in the tumor bearing mice through dextran sodium sulfate (DSS), the mice that received anti-TNFα and double checkpoint inhibition had better colitis amelioration and improved overall survival." (PMID 31439050, 2019). "Previous studies in our lab have determined that sustained production of tumor necrosis factor (TNF) and other host factors, such as sex and age, impact the fecal microbiomes of B6.129S mice with acute TNBS colitis." (PMID 31703107, 2019). "TNF blockers enhance the specific immune response, most likely by limiting the AICD of specific CD8 T cells, and neutralize the TNF-dependent colitis, and hepatitis." (PMID 31417576, 2019). "TNF-α treatment resulted in internalization and abnormal distribution of E-cadherin in WT organoids, mimicking the acute DSS colitis model." (PMID 30809073, 2019). "Induction of colitis and JGT treatment changed compositions of gut microbiota and inflammatory cytokine levels (TNF-α and IL-6)." (PMID 30800169, 2019). "For example, B. lactis treatment reduced colonic TNF-α production and the expressions of iNOS and COX-2 in TNBS model of rat colitis." (PMID 31035617, 2019). "Treatment of UC with SP, honey, and combination regimen significantly reduced TNF-α, IL-1β, IL-6, MDA, MPO, NO, and PGE2, and increased TAC, GSH, GPx, and SOD in interventional groups compared to the AA-colitis group (P<0.05)." (PMID 34466462, 2019). "We found that TOE attenuated the clinical symptoms, lowered the inflammatory scoring and inhibited the secretion of proinflammatory factors TNF‐α, IL‐1β and IL‐6 in DSS‐induced colitis." (PMID 31565850, 2019). "Apple polyphenolic extracts, soy and sulforaphane flavonoid compounds reduce pro-inflammatory cytokine expression (IL-1β, TNF-α, IL-6, IL-17, and IFN-γ) in the context of a chemically induced colitis." (PMID 31031748, 2019). "The ethanol extract of CBR, a product of A. camphorata grown on GBR, improved DSS-induced colitis in mice and this effect was attributed to the reduction in iNOS, COX-2, TNF-α and IL-6." (PMID 31717536, 2019). "Authors have also observed the reduction of mRNA expression of TNF-α, IFN-γ, IL-1, IL-2, IL-12 levels in mice with colitis." (PMID 30704060, 2019). "We previously identified the pro-inflammatory cytokine, TNFα, as a direct transcriptional target of HIF-2α, which has been critical for heightened inflammation in experimental colitis." (PMID 31461847, 2019). "Further, another study reported that Astragalus reduced NF-κB DNA phosphorylation activity and decreased the levels of TNF-α, IL-6, and MPO activity in the setting of colitis." (PMID 30610157, 2019).
colitis (continued). "B. adolescentis IF1-11 showed weak protection ability for proinflammatory factor increments, with increased TNF-α and decreased IL-10 secretion by the colonic lamina propria compared to the DSS-colitis model." (PMID 30987344, 2019). "Significantly lower concentrations of inflammatory cytokines of innate immunity (p < 0.05 for IL-1β, TNF-α, and IL-6) were observed in serum samples of DSS-treated Gal-3−/− mice at the end of induction phase of colitis." (PMID 31336879, 2019). "Surprisingly, levels of IFN-γ were highly elevated; other proinflammatory cytokines were elevated, including TNF- α and IL-6, suggesting that OVA-induced colitis is mediated through Th1 responses." (PMID 30949176, 2019). "In contrast, reduced TNFα levels in mice mediated by anti-TNFα antibody treatment or genetic Tnfa knockout, aggravated DSS- induced colitis in acute models." (PMID 30995806, 2019). "Probiotic VSL#3 inhibits the expression of NF-κB and TNF-α in rats with colitis through TLR4-NF-κB signal pathway, so it is expected to be a first choice drug for the treatment of colitis." (PMID 31497551, 2019). "We also noted that colonic levels of pro-inflammatory cytokines, such as INF-γ, IL6, IL1-β, TNF-α, and IL10, were significantly (P < 0.001) increased in mice with DSS-induced colitis, as compared to healthy mice." (PMID 28528363, 2018). "Our present study showed that the induction of colitis by DSS led to damage and inflammatory infiltration of the colonic mucosa and increased the mucosal concentration of TNF-α, IL-1β and IL-6." (PMID 29495327, 2018). "Our results showed that GABA administration reduced colon levels of inflammatory cytokines such as TNF-α, IFNγ, and IL-12 in DSS-induced colitis mice, while significantly increasing tissue levels of IL-10." (PMID 29867964, 2018). "Increases in the level of TNF-α, IL-6 and IL-1β during IBD and experimental colitis have been well documented." (PMID 30024891, 2018). "The amount of TNF-α was reduced significantly in the DSS+VNS+CMI group compared to that of the DSS+CMI group, which protected against the colitis-induced CMI aggravation and included BBB disruption, neuroinflammatory glial overreaction and oxidative stress." (PMID 30319530, 2018). "In DSS-induced colitis, the roles of TNF-α and IL-1β differ in origin and function; TNF-α is more specific to colon epithelial cells, and IL-1β is more specific to myeloid cells." (PMID 29959357, 2018). "Sulfz also abated the inflammatory mediators HMGB1, TNF-α and consequently RAGE, as compared to the colitis group." (PMID 29572553, 2018). "They observed a significant improvement of colitis under VNS, a decrease of pro-inflammatory cytokines (TNFα and IL-6), and an improvement of HRV." (PMID 32232080, 2018). "TNF-α and IL-17 play an important role both in the pathogenesis of IBD and in experimental TNBS-induced colitis." (PMID 28337639, 2018). "Levels of proinflammatory cytokines, such as TNF, IFN-γ, IL-6, IL-12, IL-17A, and IL-23 were elevated in the serum of DSS-induced colitis mice." (PMID 29892282, 2018). "The detected concentrations of the two cytokines TNF-α and IL-6 showed that their levels decreased after TRYP treatment of the colitis." (PMID 29724065, 2018). "In our study, administration of fargesin suppressed the excessive NO production in DSS-colitis mice and downregulated iNOS, COX-2, and TNF-α protein expression in LPS-stimulated RAW264.7 cells." (PMID 29880739, 2018). "Genetic studies have shown that inflammatory cytokines, such as TNFα, IL-1β, IL-6, and IFN-γ, are elevated in colitis, and are important in the development of mucosal inflammation." (PMID 29467753, 2018). "In this study, we found that supplemented with Farrerol significantly suppressed the production of pro-inflammatory cytokines TNF-α, IL-6 and IL-1β in TNBS-induced colitis mice." (PMID 30011811, 2018).
colitis (continued). "In fact, as in TNBS-induced colitis, VNS reduced the serum levels of pro-inflammatory cytokines, i.e. IL-6, CXCL1, and TNFα, and dampened the colonic expression of IL-6 and CXCL1 in the oxazolone-induced colitis model." (PMID 29791477, 2018). "The cPLA2 inhibitor pyrrophenone ameliorated colitis in terms of DAI, histological inflammation, and score, colon length, and the colonic levels of TNF-α and LTB4." (PMID 29494494, 2018). "In this study, we demonstrated that IFN-γ, IL-12, TNF-α, and IL-6 increase in DSS-induced colitis mice." (PMID 28587089, 2017). "In contrast, such an elevation in the plasma levels of TNF-α, MCP-1, IL-6 and IL-13 was significantly attenuated in the HFD mice subjected to voluntary exercise prior to the induction of colitis (p < 0.05)." (PMID 28425943, 2017). "PSMP overexpression in the colon aggravated the DSS-induced colitis and the anti-PSMP neutralizing antibody mollified the colitis by reducing macrophage infiltration and inhibiting the expression of IL-6, TNF-α and CCL2." (PMID 28698550, 2017). "The administration of monoclonal antibodies against IL-6 and TNF-α was able to reduce disease severity and attenuate intestinal inflammation in DSS-induced colitis." (PMID 28194046, 2017). "Here, we demonstrated that PSMP was expressed in the colonic mucosa of patients with colitis and significantly up-regulated in the initial stage prior to the expression of IL-6, TNF-α and CCL2 in a DSS-induced colitis in mice." (PMID 28698550, 2017). "The expression of mRNA for TNF-α, IL-6 and MCP-1 was significantly decreased in the mesenteric white tissue of the mice with TNBS colitis subjected to voluntary exercise as compared to the group maintained without voluntary exercise (p < 0.05)." (PMID 28425943, 2017). "IL-6, CCL2, TNF-α, and IFN-γ in the mIgG-treated colitis group were extremely elevated and significantly decreased in the 3D5-treated colitis group." (PMID 28698550, 2017). "The effects of lactobacilli and bifidobacteria administration on TNF-α and TLR4 expression in a rat colitis model induced by TNBS were also investigated." (PMID 28555037, 2017). "Colitis rats also had higher MPO activity (indicating neutrophil infiltration into the damaged tissue), higher pro-inflammatory cytokine levels, including TNF-α, IL-1β, and IL-8." (PMID 29176974, 2017). "The data in this paper revealed that the expression levels of IL-17, IL-21, IL-23, IL-6, IL-1β, TNFα, and IL-12 in mLN tissues significantly decreased in CD169-DTR colitis mice compared to those in WT colitis mice." (PMID 28694804, 2017). "PSMP is up-regulated in the initial stage prior to IL-6, TNF-α and CCL2 up-regulated expression in DSS colitis and promote the M1 macrophages to produce CCL2." (PMID 28698550, 2017). "mRNA expression of iNOS, ICAM-1, MCP-1, COX-2, TNF-α and IL-1β was remarkably induced in the colonic tissues of TNBS-colitis mice." (PMID 29180692, 2017). "Simultaneously, cytokines, including PSMP, IL-6, CCL2, TNF-α, IFN-γ and IL-10 in the colon homogenates were measured with CBA in the time-course study of colitis." (PMID 28698550, 2017). "Our findings are in agreement with previous data showing the overexpression of TNF-α and NOS2 in the inflamed intestinal mucosa in UC patients, human colon carcinoma tissue, and murine model of carcinoma arising on colitis." (PMID 28408791, 2017). "A previous study performed by our research group demonstrated that grape juice treatment decreased the TNF-alpha and iNOS gene and immunoexpression, as well as DNA damage in TNBS-induced colitis models." (PMID 28868268, 2017). "Reduces inflammation in a mouse model of DSS-induced colitis, probably by increasing the expression of anti-inflammatory cytokines (IL-10 and TGF-β) and reducing pro-inflammatory ones (IL-6 and TNF-α)." (PMID 29163443, 2017). "TNF-α produced by macrophages and endothelial cells is necessary for the initiation and persistence of TNBS-induced colitis." (PMID 28556814, 2017).
colitis (continued). "Data from animal models indicate that OLE attenuates the inflammatory process in DSS-induced colitis by downregulating the expression of COX-2 and pro-inflammatory cytokines, such as TNF-alpha, IL-1β, IL-6 and IL-17." (PMID 28420140, 2017). "According to our data, baicalein effectively inhibited the mRNA expression of iNOS, ICAM-1, COX-2, MCP-1, TNF-α and IL-1β in the colon of TNBS-colitis mice." (PMID 29180692, 2017). "PSMP was up-regulated in the initial stage prior to IL-6, TNF-α and CCL2 up-regulated expression in DSS colitis and promoted the M1 macrophages to produce CCL2." (PMID 28698550, 2017). "Compared with normal rats, the levels of many cytokines including IL-6, TNF-α, IL-17, IL-23, IL-1βand IFN-γ were increased, while IL-13, IL-10 and IL-4 were decreased in TNBS-induced colitis rats." (PMID 29113344, 2017). "In this study, PSMP increases were observed in the initial stage in the DSS-induced colitis model; at this time, CCL2, IL-6 and TNF-α were still expressed at low level." (PMID 28698550, 2017). "The expression of mRNA for TNF-α, IL-6 and MCP-1 was significantly increased in the sedentary mice fed a HFD as compared to the sedentary mice with colitis fed a SD." (PMID 28425943, 2017). "In the sedentary group fed a SD, the plasma TNF-α, MCP-1, IL-6 and IL-13 were negligible but in the mice with colitis, a significant increase in the plasma levels of these cytokines was observed (p < 0.05)." (PMID 28425943, 2017). "The administration of HQD, however, significantly suppressed the accumulation of TNF-α, IL-6, IL-1β, and COX-2 in the colon tissues of mice with DSS-induced colitis." (PMID 28415628, 2017). "Tumour necrosis factor alpha (TNF-α), Interleukin 6 (IL-6), Interleukin 1 beta (IL-1β), and cyclooxygenase-2 (COX-2) play a pivotal role in the onset of colitis." (PMID 28415628, 2017). "In a mouse model of DSS-induced colitis, intraperitoneal administration of ADM was shown to inhibit colon inflammation, and research has shown that administration of ADM reduces the levels of cytokines such as TNF-α, IL-1β, and IL-6." (PMID 28210268, 2017). "HdAg has been shown to relieve DSS-induced colitis, with decreased expression of IFN-γ, IL-17, and TNF and increased expression of IL-10." (PMID 29163443, 2017). "During this process, macrophages play a key role because they can release large amounts of proinflammatory cytokines, such as interleukin (IL)-1, IL-6, and tumor necrosis factor (TNF)-α, which exacerbate the severity of the inflammation condition and colitis." (PMID 29354126, 2017). "We observed that the colonic levels of TNF-α and IL-6 in the DSS-induced colitis mice were markedly decreased by ULP-SeNPs, as measured by ELISA." (PMID 28270147, 2017). "The contribution of AnxA1 to the remission of IBD was validated with a model of dextran sulfate sodium (DSS)-induced colitis in TNFR knockout (KO) mice, mimicking the anti-TNF-α therapy." (PMID 27199985, 2016). "So, while circulating TNFα and IL-17 levels seem to correlate with the DSS colitis clinical course, IL-1β, and IL-10 mainly correlate with the histological damage that tends to become chronic." (PMID 26973525, 2016). "The ApoE-mimetic peptide COG112 was shown to block production of many inflammatory factors including TNF-α, KC, IL-17 and MIP-2 potentially by preventing nuclear accumulation of NF-κB and activation of IKK in CECs in a model of colitis." (PMID 27538678, 2016). "The transcriptional activity of STAT3 has been suggested to induce TNF-α production and plays a role in the pathogenesis of DSS induced colitis." (PMID 27258062, 2016). "Significantly attenuated levels of inflammatory cytokines TNF-α, MPO, macroscopically visible damage score, and colon weight-to-length ratio were responsible for the resistance to colitis recurrence in Sal B treated group." (PMID 27303297, 2016). "GA regulates the levels of inflammatory mediators such as IL-6, TNF-α, and IL-1β in DSS-induced colitis in mice." (PMID 27110761, 2016).
colitis (continued). "Because H-SN1 is a TNFR1-binding peptide, we also investigated the effect of H-SN1 on TNF-α-mediated NF-κB and MAPK pathway activation in the colonic tissue of mice with colitis." (PMID 27158082, 2016). "DSS-induced colitis studies have proved that MMP-9 activity increases in homogenates of colonic mucosa in UC and is dependent on TNF-alpha." (PMID 27034654, 2016). "In conclusion, the current study clearly demonstrates that alpinetin can effectively inhibit the expression of TNF-α and IL-1β in DSS-induced mouse colitis." (PMID 27321991, 2016). "LL202 inhibited the high-production of IL-1β, IL-6 and TNF-α dramatically both in the colon and serum of DSS-induced colitis mice." (PMID 27590510, 2016). "Pro-inflammatory cytokines (TNF-α, IL-1β, and IL-6) levels and MPO activity from colitis rat colon tissue were significantly increased compared to those in sham group." (PMID 27303297, 2016). "The circulating TNFα level correlates with clinical activity both in ulcerative colitis and Crohn's disease and increases in acute phases of DSS colitis." (PMID 26973525, 2016). "The key effect of the 13 reference genes on quantifying relative mRNA expression of two target genes (TNF-α and IL-1β) in DSS-experimental colitis was investigated using comparative the ΔΔCt method." (PMID 27244258, 2016). "Because TNBS-induced colitis leads to marked inflammation in a pattern that is similar to that described for CD, the levels of the proinflammatory cytokines IL-12, IFN-γ, TNF-α, IL-6 and IL-17A were analysed." (PMID 27576902, 2016). "Conjugated leinoleic acids suppress TNF-α and MCP-1 colonic expression and reproduce the effects of VSL#3 administration in mice with Disodium sulfate colitis." (PMID 27994577, 2016). "Naringenin abrogated experimental colitis by downregulating proinflammatory mediators like iNOS, ICAM-1, monocyte chemoattractant protein-1, COX-2, TNF-α, and IL-6." (PMID 27635116, 2016). "A recent report showed reduced colitis severity by treatment with the macrolide 7-O-succinyl macrolactin A (SMA), which was mediated in part through inhibiting TNF-induced PI3K, AKT, mTOR and p70S6 kinase phosphorylation." (PMID 27997590, 2016). "Specific Lactobacillus reuteri strains suppress production of the proinflammatory cytokine, tumor necrosis factor (TNF), and are protective in a mouse model of colitis." (PMID 27353144, 2016). "Administration of rifaximin after induction of colitis has decreased the activity of MPO and reduced concentration of IL-1β and TNF-α in colonic mucosa, reflecting the reduction in the local inflammatory reaction." (PMID 27433160, 2016). "In patients with IBD, the production of the inflammatory cytokines TNF-α, IFN-γ, IL-6, IL-1β, IL-10 and IL-12 are in agreement with the results of the TNBS model of colitis." (PMID 26561804, 2015). "Furthermore, the administration of anti-TNF-α antibody (infliximab) is effective in improving the clinical status of the patients with Crohn’s disease and the injection of anti-IL-6 receptor antibody in mice with colitis resulted in inhibition of IFN-γ, IL1-β mRNA as well as TNF-α secretion." (PMID 25853847, 2015). "Disease establishment took place at ~15 weeks old animals when the expansion of CD4+ T-cells expressing IL-17, TNF and IFN-γ reached a threshold together with stabilization of colitis severity and accumulation of B272 molecules." (PMID 26125554, 2015). "We found a significant increase in the levels of IL-1β, IL-6, IL-17, TNF-α and IFN-γ in the plasma of mice with colitis." (PMID 25625560, 2015). "Furthermore, in the acute DSS colitis mouse model, anti-TNF treatment reduced expression of gene targets that might mediate epithelial cell injury; and in chronic DSS colitis it abrogated elevated levels of cleaved caspases 3 and 9, highlighting the importance of apoptosis in these conditions." (PMID 25919700, 2015).